VWF (von Willebrand factor)
Diseases named in the same sentence as VWF in open-access papers (continued):
Sharing a sentence is not in itself a finding about the gene and the disease.
ischemia (22 papers, 2008 to 2025). A hypoperfusion of the BLOOD through an organ or tissue caused by a PATHOLOGIC CONSTRICTION or obstruction of its BLOOD VESSELS, or an absence of BLOOD CIRCULATION. "This may be associated with the depletion of vWF levels during the onset of ischemia, leading to the development and progression of HT." (PMID 40135640, 2025). "Once activated, endothelial cells secrete endothelin-1 (ET-1), von Willebrand factor (vWF), nitric oxide, and endothelial nitric oxide synthase, resulting in unstable vascular tone, with decreased vasodilation and increased vasoconstriction causing ischemia and tissue hypoxia." (PMID 37886934, 2023). "This accumulates ultra-large von Willebrand factor multimers that can embolize and occlude arterioles, leading to widespread microvascular ischemia." (PMID 35812544, 2022). "Insufficiency of ADAMTS-13 leads to the accumulation of very large vWF multimers, while the spontaneous formation of microthrombi in arterioles and capillaries is induced, followed by the development of ischemia." (PMID 35887770, 2022). "A significant decrease in VEGFR2 and vWF expression levels was observed in the ischemia group compared with the control group." (PMID 34630958, 2021). "Rats treated with BM-MSCs showed significantly raised gene expression levels of SDF-1, CXCR4, VEGFR2, and vWF compared with control and ischemia groups." (PMID 34630958, 2021). "Conversely, gene expression levels of VEGFR2 and vWF significantly increased in rats treated with BM-MSCs relative to the control and ischemia groups." (PMID 34630958, 2021). "Two further studies also corroborate the contention that VWF/GPIbα-bound platelets are capable of promoting neutrophil recruitment/extravasation in murine models of ischemia/reperfusion via P-selectin-independent mechanisms." (PMID 32314961, 2020). "Increased leakage of the exogenous tracer Sulfo-NHS-Biotin, as an indicator of BBB integrity, was observed in vWF-positive cells of MCAO rats after ischemia." (PMID 33584203, 2020). "These indicate that ADAMTS13 protects the brain from ischemia-reperfusion injury predominantly through cleaving the endothelial cell-derived VWF." (PMID 31379722, 2019). "VWF is also described as a pro-inflammatory mediator of leukocyte extravasation which is - among others - one important step during the onset of ischemia leading to pro-inflammatory activity in the ischemic brain." (PMID 23935828, 2013). "A decrease in the activity of a disintegrin-like and metalloproteinase with thrombospondin type 1 motifs 13 (ADAMTS13), a VWF-cleaving enzyme, allows unusually large VWF multimers to form unusually large platelet thrombi in blood vessels, leading to ischemia-induced organ damage." (PMID 38732176, 2024). "The release of endothelin-1 may promote vasoconstriction, whereas the production of von Willebrand factor (vWF) shifts the hemostatic balance towards a procoagulant state, resulting in coronary arteries’ thrombosis, and subsequent ischemia." (PMID 36837440, 2023). "However, our previous work demonstrated that VWF: CB elevation characterizes critical ischemia and together with VWF: Ag is significantly correlated to plasma osteoprotegerin (OPG)." (PMID 35453881, 2022). "Apart from decreased blood flow, accumulation of inflammatory cells was observed in the brains of ADAMTS13−/−mice, suggesting that ADAMTS13 may protect the brain from ischemia by regulating VWF-dependent inflammation after reperfusion." (PMID 31379722, 2019). "Morever, the increase in the amount of vWF+ vessels induced by ischemia could be extended to 28 days after administration of morroniside, indicating the crucial role of morroniside in angiogenesis during the chronic phase." (PMID 24979385, 2014). "However, administration of morroniside (90 mg·kg−1·and 270 mg·kg−1) enhanced the amount of vWF+ vessels at 28 days after ischemia, suggesting that morroniside plays a crucial role in angiogenesis during the chronic phase." (PMID 24979385, 2014).
ischemia (continued). "Hence, compounds that target VWF could have the attractive potential to promote acute thrombolysis in the occluded blood vessel and attenuate ischemia/reperfusion injury in the microvasculature of the affected brain territory." (PMID 31921147, 2019). "The increased expression of vWF in the 6wMP rats and 12wMP rats suggests that the application of TDFE relieved the ischemia and hypoxia of the sciatic nerves." (PMID 27057201, 2016). "In animal studies, we analyzed the effects of atorvastatin or rosuvastatin treatments in recovery of capillary density and blood flow, the expression of vWF and CXCR4 at ischemia sites in hindlimb ischemia ICR mice." (PMID 26309120, 2015). "Double-immunofluorescent labelling of brain slices from rats 24 h post-ischemia confirmed that these STI-1-expressing cells included Neu-N+ neurons, GFAP+ glia, MAP-2+ neurons and vWF+ vascular endothelial cells." (PMID 23836498, 2013). "Not surprisingly, with a decrease in VWF levels in all groups from baseline through basilar artery access and ischemia came a concurrent increase in ADAMTS13 levels to continually cleave the large multimeric VWF into a manageable size for further degradation." (PMID 39445200, 2024). "Similarly, we find no clear evidence of co-expression of GFP and vWF/CD31, although such co-expression has been previously reported at later times of observation (3 days – 1 month) after induction of ischemia." (PMID 18947400, 2008). "Interestingly, the significant attenuation in VEGFR2 and vWF levels and the non-significant decrease in the level of SDF-1 gene expression in the ischemia group compared with the control group in the current work may be related to the time and course of ischemia." (PMID 34630958, 2021).
viral infection (22 papers, 2014 to 2025). "In this regard, the expression levels of VCAM1, vWF (von Willebrand factor), P‐selectin (a type‐1 trans‐membrane protein), and E‐selectin (an adhesion receptor) increased significantly upon viral infection in the mid‐aged mice ECs." (PMID 38098255, 2024). "Endothelial cell damage due to the viral infection results in subendothelial collagen exposure initiating von Willebrand factor (vWF) binding via its A3 domain." (PMID 36768817, 2023). "Hypercoagulability phenomena induced by this viral infection appear to be related to altered von Willebrand factor activity, alteration of the renin–angiotensin–aldosterone system, and dysregulation of both innate and adaptive immunity." (PMID 37686216, 2023). "Viral infection of endothelial cells triggers their activation and injury, initiating a pro-inflammatory response characterized by the release of cytokines and upregulation of von Willebrand factor (VWF) and adhesion molecules." (PMID 41425980, 2025). "In particular, vWF, HRG, PROS1, GC, F2, FGA, and FGB proteins, which are responsible for the expansion of vessels and new vessel formation, modulate blood coagulation and mitigate against vasoconstriction and coagulation caused by virus infection." (PMID 35401544, 2022). "However, this possibility is unlikely, as a change in von Willebrand factor is usually either due to high shear stresses or an antibody against von Willebrand factor, and has never been associated with a viral disease." (PMID 31262565, 2019). "Von Willebrand factor (vWf) has been shown to be released during CMV infection, and, among 39 patients with recent kidney transplantation and acute CMV infection, increased vWf and soluble vascular cell adhesion molecule 1 (sVCAM-1) in the peripheral blood were correlated with viral infection." (PMID 24678987, 2014).
liver fibrosis (21 papers, 2014 to 2025). "Well-established diagnostic biomarkers for liver fibrosis, including alpha-2-macroglobulin (A2M) and von Willebrand factor (VWF), have significant drawbacks, such as insufficient specificity and individual variability." (PMID 40943308, 2025). "Coagulation factors, including FVIII and other molecules involved in hemostasis, such as VWF, have been implicated in the progression of liver fibrosis, while factors such as ADAMTS13 have shown potential in reducing fibrogenesis." (PMID 37443746, 2023). "On the other hand, vWF is an angiogenic-associated factor and had been enhanced in dimethylnitrosamine induced liver fibrosis rat model." (PMID 29156788, 2017). "VWF: Ag was associated with liver fibrosis; it might help anticipate the emergence of HCC." (PMID 39859975, 2024). "The ROC analysis for plasma VWF in predicting mild (F1-2) and severe (F5-6) liver fibrosis yields a statistically significant and excellent AUC, with a 95% confidence interval." (PMID 40764410, 2025). "Our investigation assessed Von-Willebrand Factor Antigen (VWF Ag) plasma titer as a probable non-invasive predictor for grading liver fibrosis in children with CLD." (PMID 40764410, 2025). "The rise in VWF titer during liver fibrosis has been attributed to several mechanisms, including endothelial damage induced by bacterial components that enhance VWF secretion." (PMID 40764410, 2025). "HE staining, Masson staining, and the IHC staining showed an increase in COL1A1 and vWF protein expression in the first stage of CCl4-induced liver fibrosis." (PMID 36497176, 2022). "The detection of fibrin deposits and expression of vWF suggested thrombosis as another mechanism of liver fibrosis, which has been described by others." (PMID 35369312, 2022). "The current investigation was intended to determine if VWF Ag titer could identify and classify the degree of liver fibrosis in children with CLD." (PMID 40764410, 2025). "Finally, advanced liver fibrosis is characterized by extensive vascular remodeling, affecting endothelial cell types and their products such as von Willebrand factor (vWF)." (PMID 38396688, 2024). "At a stage of severe liver fibrosis, the VWF: Ag area under the curve was 0.721." (PMID 39859975, 2024). "Besides miRNA-122, further research on non-invasive markers has been published as the enhanced liver fibrosis panel, von Willebrand factor, circulating marker of collagen type III, type IV and V." (PMID 25646812, 2015). "VWF may therefore be related to the progression of liver fibrosis." (PMID 36002595, 2022). "Reduction of A2 by RNA silencing (siRNA) in hepatocellular and liver fibrosis cell lines significantly reduced vWF secretion, suggesting that hepatocyte-driven vWF secretion, in addition to the release of vWF by endothelial cells, may contribute to liver fibrosis." (PMID 34202091, 2021). "During the progression of liver fibrosis, LSECs exhibit a marked increase in the expression of CD31, CD34, and molecules such as von Willebrand factor (VWF)." (PMID 40573288, 2025). "Thus, VWF, A2M, F3, and MME are crucial biomarkers for liver fibrosis, particularly during active disease phases." (PMID 40943308, 2025). "Those who had developed HCC or were in a severe state of liver fibrosis had greater VWF antigen (VWF: Ag) levels than those who had not." (PMID 39859975, 2024). "Another study investigated whether VWF may be a biomarker for the development of HCC and liver fibrosis." (PMID 39859975, 2024). "Another study indicated that VWF levels were higher in patients with severe liver fibrosis stage and/or HCC development than in those without." (PMID 37950277, 2023). "Furthermore, vWF increases with fibrosis stage in hepatitis C and NASH patients, supporting this as a potential marker of advancing hepatic fibrosis." (PMID 34572384, 2021). "SVEP1 and VWF may be promising biomarkers for auxiliary diagnosis of HCC and liver fibrosis." (PMID 36002595, 2022).
metabolic syndrome (21 papers, 2011 to 2024). A cluster of metabolic risk factors for CARDIOVASCULAR DISEASES and TYPE 2 DIABETES MELLITUS. "Cigarette smoking was associated with increased dyslipidemia, BMI, and central obesity, in addition to higher vWF functional activity." (PMID 39072281, 2024). "In acute inflammation, such as that caused by accidental injury, and chronic inflammation, such as that caused by metabolic syndrome and cancer, vascular endothelial cells express pro-inflammatory and thrombus-promoting factors such as VWF, TF, and IL-6." (PMID 35200650, 2022). "Several studies have observed an association between dyslipidemia and VWF in patients with T2D and may point to how dyslipidemia contributes to endothelial damage in this population." (PMID 36984822, 2023). "In a Czech study, significantly higher PEDF was found in type 2 diabetic patients with metabolic syndrome; and the von Willebrand factor was independently associated with PEDF in type 2 diabetic patients without metabolic syndrome indicating the potential angio-protective role of PEDF in diabetes." (PMID 36837889, 2023). "We previously reported little effect of DE on markers of thrombosis including D-Dimer, von-Willebrand factor in metabolic syndrome subjects, or in healthy subjects." (PMID 23531317, 2013). "However, vWF did not correlate with age, but was independently associated with indicators of mixed dyslipidemia (TG and HDL-C levels)." (PMID 36984822, 2023). "Interestingly, in a similar study conducted in volunteers with metabolic syndrome, hypothesized to be more susceptible to cardiovascular risk, again no significant increase in D-dimer, vWF, and PAI-1 was observed after DE100 and DE200 exposure." (PMID 35139881, 2022). "Thus, we assumed that early intervention with vitamin D in patients with metabolic syndrome and related disorders may be important; while the beneficiary effect of vitamin D on vWF may be increased when individuals have longer duration of supplementation and similar baseline levels of vWF." (PMID 30519274, 2018). "The results have suggested that GXNT could regulate dyslipidemia, improve heart function, and inhibit the levels of ox-LDL, CRP, TNF-α, IL-1β, SOD, MDA, vWF, and ET-1, as well as platelet aggregation." (PMID 35935588, 2022). "This meta-analysis showed that taking vitamin D significantly improved vWF, but did not affect other markers related to endothelial activation among patients with metabolic syndrome and related disorders." (PMID 30519274, 2018). "Overall, the current meta-analysis demonstrated that vitamin D supplementation to patients with metabolic syndrome and related disorders resulted in an improvement in vWF, but did not affect ICAM-1, VCAM-1, E-selectin and endothelin levels." (PMID 30519274, 2018). "This meta-analysis demonstrated that vitamin D supplementation to patients with metabolic syndrome and related disorders resulted in a significant decrease in vWF, but did not affect other markers of endothelial activation." (PMID 30519274, 2018). "Therefore, the aim of our study was to evaluate association between vWF activity, inflammation markers, disease activity, and carotid IMT in young, non-diabetic, normotensive, female RA patients, with no dyslipidemia." (PMID 26247590, 2015). "vWF and TNF-α compared to subjects without metabolic syndrome; in CEI group with metabolic syndrome IL-6, TNF-α and v-WF were more positively and significantly related to AIx compared to subjects without metabolic syndrome." (PMID 24571954, 2014).
glioma (20 papers, 2015 to 2025). A benign or malignant brain and spinal cord tumor that arises from glial cells (astrocytes, oligodendrocytes, ependymal cells). "This study shows that CD34, VWF, and AQPs are associated with post-IR GSCs glioma relapse and provides essential insights for the development of treatment regimens for radioresistant tumors." (PMID 31803626, 2019). "High levels of VWF were also associated with a worse survival even in lower grade gliomas." (PMID 35327035, 2022). "We also explored alterations in transcriptional regulatory mechanisms that are associated with activation of the VWF gene transcription in cancer cells, and also demonstrated presence of VWF expressing cancer cells in patient's tumor samples of glioma and osteosarcoma." (PMID 28035064, 2017). "Research demonstrated the de novo expression of VWF in glioma, suggesting a potential new avenue for understanding its involvement in brain tumors." (PMID 39906820, 2025). "VWF has also been proposed as a biomarker that has a predictive value for an early three-month response in recurrent glioma to bevacizumab treatment, a neutralizing monoclonal antibody against a vascular endothelial growth factor ligand." (PMID 35327035, 2022). "Non-endothelial-origin tumor cell lines, such as osteosarcoma, colorectal cancer, hepatocellular carcinoma (HCC), gastric cancer, and gliomas, have been shown to produce VWF." (PMID 35327035, 2022). "Quantitative PCR were performed on the DNA isolated from SAOS2 and KHOS, as well as malignant glioma U251 (a glioma cell line that also expresses VWF) and HUVECs, subjected to digestion by methylation sensitive restriction enzymes." (PMID 28035064, 2017). "Besides, the high expression of von Willebrand factor (VWF) has been confirmed in GBM plasma, which not only serves as a diagnostic marker for glioma but also distinguishes BrM that can be considered a strong candidate biomarker." (PMID 39716938, 2025). "Besides EC and platelets, many tumor cells of non-endothelial cell origin, such as osteosarcoma, gastric adenocarcinoma, and gliomas, also have the ability to express and store VWF." (PMID 39282473, 2024). "We demonstrated de novo expression of VWF in glioma as well as osteosarcoma cells." (PMID 28035064, 2017). "Collectively these findings indicate that a 3D-induced tumour microenvironment is sufficient to promote expression of the endothelial markers CD105, CD31 and vWF in a proportion of high grade glioma and ependymoma cells that reside in distinct tumour aggregate regions." (PMID 26203665, 2015). "In the BrM/Glioma group, 8 DEPs (PRL, SNCA, MACF1, ACAT2, VWF, GSN, FCGBP, and F10) were selected for ROC curve analysis based on a logistic regression model." (PMID 39716938, 2025). "In the Glioma/NC group, 8 proteins (COL1A1, PRL, VWF, HBD, SF3B1, NME3, RRBP1, and CSRP1) were selected, with an AUC of 0.892 in the training set and 0.871 in the validation set (accuracy: 78.5%)." (PMID 39716938, 2025). "VWF expression has also been found in histopathological samples of patients with osteosarcoma, HCC, gliomas, and gastric carcinomas." (PMID 35327035, 2022). "Human glioma stem/progenitor cells can transdifferentiate into vascular endothelial cells (VECs) and express VECs markers including CD31, CD34, and vWF significantly under hypoxia." (PMID 27346985, 2016). "Trans-differentiation of glioma cells to endothelial cells in vitro was demonstrated by culturing of glioma cancer stem cells in endothelial-promoting media, resulting in expression of pan-endothelial markers CD31, CD34 and vWF, formation of tubular structures and uptake of LDL." (PMID 31690961, 2020). "However, a few studies have reported that vWF-MVD and CD105-MVD may predict the malignancy grade and prognosis of gliomas." (PMID 30176826, 2018). "Analyses of the VWF promoter in a VWF expressing glioma cell line were similar (data not shown)." (PMID 28035064, 2017).
glioma (continued). "FAP+ cells were efficiently propagated in conditions suitable for pericytes, expressed mesenchymal markers PDGFRβ, αSMA, and TE-7, but were negative for glioma (GFAP) and endothelial (vWf) markers." (PMID 34282761, 2021). "Because the levels of vWF, MMP9, VCAM1, angiogenin, and HGF were increased in both GBM and MI patients, but not in the lower-grade gliomas, these factors seem to be necessary for neovascularization in general, both under reactive and high-grade neoplastic conditions." (PMID 31428150, 2019). "Based on these reports, we explored whether some cancer cells of non-endothelial origin, including glioma as well as osteosarcoma SAOS2, acquire de novo transcription of the VWF gene and determined the functional consequences with regard to tumor cell adhesion and extravasation." (PMID 28035064, 2017).